ALOX5AP (arachidonate 5-lipoxygenase activating protein)
Description:
Required for leukotriene biosynthesis by ALOX5 (5-lipoxygenase). Anchors ALOX5 to the membrane. Binds arachidonic acid, and could play an essential role in the transfer of arachidonic acid to ALOX5. Binds to MK-886, a compound that blocks the biosynthesis of leukotrienes.
Synonyms: FLAP
Tractability: Small molecule: a drug acting on it is in phase 2 or 3 trials; a structure with a bound ligand is known; a high-quality ligand is known; it has a high-quality binding pocket; it belongs to a druggable protein family. Antibody: UniProt predicts a signal peptide or a membrane-spanning region. PROTAC: its protein half-life has been measured; a small molecule that binds it is known.
Target class: Other cytosolic protein
Chemical probes: BI 665915 (high quality), FIBOFLAPON (high quality)
Gene: Protein-coding gene on chromosome 13 (30,713,478 to 30,765,072, forward strand). Ensembl gene ENSG00000132965.
Subcellular location: Nucleus membrane; Endoplasmic reticulum membrane
Pathways (Reactome):
Metabolism: Biosynthesis of Lipoxins (LX); Synthesis of 5-eicosatetraenoic acids; Synthesis of Leukotrienes (LT) and Eoxins (EX)
Gene Ontology:
Molecular function: arachidonate binding; protein binding; glutathione peroxidase activity; glutathione transferase activity; leukotriene-C4 synthase activity; enzyme activator activity
Biological process: cellular response to calcium ion; leukotriene biosynthetic process; protein homotrimerization; carboxylic acid biosynthetic process; cellular oxidant detoxification; leukotriene metabolic process
Cellular component: endoplasmic reticulum; membrane; nuclear envelope; nuclear membrane; endoplasmic reticulum membrane
Genetic constraint (gnomAD): Loss-of-function variants: 9 observed, 19.75 expected, observed/expected ratio (o/e) 0.46, 90% interval 0.27 to 0.8. The upper end of that interval is the gene's LOEUF score, 0.8, which puts it in group 3 of 6, group 1 being the genes least tolerant of losing a copy. Missense variants: 172 observed, 212.44 expected, observed/expected ratio (o/e) 0.81, 90% interval 0.71 to 0.92. Synonymous variants: 81 observed, 83.22 expected, observed/expected ratio (o/e) 0.97, 90% interval 0.81 to 1.17.
Homologues: Orthologues: chimpanzee ALOX5AP (100% identical), macaque ALOX5AP (98% identical), rabbit ALOX5AP (95% identical), guinea pig ALOX5AP (94% identical), mouse Alox5ap (92% identical), pig ALOX5AP (91% identical), dog ALOX5AP (86% identical), rat Alox5ap (81% identical), tropical clawed frog alox5ap (80% identical), zebrafish alox5ap (56% identical). Paralogues in human: LTC4S (32% identical), MGST2 (30% identical), MGST3 (19% identical).
Diseases named in the same sentence as ALOX5AP in open-access papers:
ALOX5AP is named in the same sentence as 96 diseases in open-access papers, as found by Europe PMC text mining. Sharing a sentence is not in itself a finding about the gene and the disease. The quoted sentences say what the papers report.
myocardial infarction (25 papers, 2008 to 2025). Gross necrosis of the myocardium, as a result of interruption of the blood supply to the area, as in coronary thrombosis. "Genetic variability in ALOX5AP has also been associated with myocardial infarction in the German population." (PMID 36011386, 2022). "ALOX5AP is known from literature knowledge synthesis to be associated with ischemic stroke, myocardial infarction, atherosclerosis, cerebral infarction, and coronary artery disease." (PMID 33024578, 2020). "Previous studies have reported that genetic variations in ALOX5AP exhibit significant associations with ischemic stroke and myocardial infarction." (PMID 31180540, 2019). "Two studies in European populations and a meta-analysis found ALOX5AP associations with stroke, myocardial infarction, and coronary artery disease (CAD), but two separate studies and an additional meta-analysis did not." (PMID 25210744, 2014). "In this study, another 4-SNP haplotype of ALOX5AP, called HapB, in the United Kingdom population was also associated with a 2 times greater risk of myocardial infarction." (PMID 19578513, 2008). "A 4-SNP haplotype, called HapA, in the gene ALOX5AP on chromosome 13q12–13 for encoding FLAP was associated with a two times greater risk in myocardial infarction and stroke." (PMID 19578513, 2008). "ALOX5AP (also known as 5-lipoxygenase activating protein, FLAP) is required for leukotriene synthesis; it has been implicated in inflammatory responses, stroke, and myocardial infarction; and it is an indicator for predicting high CD8+ tumor infiltration and a “hot” tumor microenvironment." (PMID 40460345, 2025). "Diseases associated with ALOX5AP include stroke, ischemia, and myocardial infarction." (PMID 39108264, 2024). "Genetic variants in another member of the leukotriene pathway, ALOX5AP, may be associated with the pathogenesis of both myocardial infarction and stroke by increasing leukotriene production and increasing inflammation in the arterial wall." (PMID 36011386, 2022). "Moreover, ALOX5AP has been previously associated with atherosclerosis, whereas its haplotypes have been associated with myocardial infarction." (PMID 30678701, 2019). "Genetic variations in Alox5ap may be associated with susceptibility to myocardial infarction and stroke through an increase in leukotriene production and inflammation in the arterial wall." (PMID 31827539, 2019). "Recently, a variant of the gene encoding LTB4 hydrolase (LTA4H), a protein in the same biological pathway as ALOX5AP has been shown to be associated with risk of myocardial infarction, further strengthening the case for a role of the lipoxygenase pathway on CVD risk." (PMID 20592751, 2010). "ALOX5AP (aka FLAP) is required for leukotriene synthesis; it has been implicated in inflammatory responses, stroke, and myocardial infarction; and it is an indicator for predicting high CD8+ tumor infiltration and a “hot” tumor microenvironment." (PMID 38853836, 2024). "The same study showed that lncRNA AY212271 is coexpressed with Alox5ap and can participate in the inflammatory response in the border zone of myocardial infarction indirectly through Alox5ap." (PMID 36011386, 2022). "Polymorphisms of the ALOX5AP gene encoding FLAP contribute to the risk of coronary heart disease in patients with familial hypercholesterolemia, as well as the development of myocardial infarction." (PMID 35563200, 2022). "For example, Alox5ap is reported to be involved in myocardial infarction with a degree of 49.27 (MalaCards score)." (PMID 31827539, 2019). "In the co-expression network, we found 16 genes directly involved in myocardial infarction, including Alox5ap, Itgb2 and B4galt1." (PMID 31827539, 2019). "Gene ALOX5AP (ENTREZ GENE # 241) has been related with myocardial infarction and stroke, and also with inflammatory activity and atherosclerosis." (PMID 25329069, 2014). "Similar results were reported in a study on myocardial infarction and the ALOX5AP pathway." (PMID 36673783, 2023).
myocardial infarction (continued). "One study showed that ALOX5AP is directly involved in myocardial infarction." (PMID 35475279, 2022). "Genetic variation in the genes ALOX5 (arachidonate 5-lipoxygenase), ALOX5AP (arachidonate 5-lipoxygenase-activating protein) and LTA4H (leukotriene A4 hydrolase) has previously been shown to contribute to the risk of MI (myocardial infarction) in Caucasian and African American populations." (PMID 30678701, 2019). "Variations in the ALOX5AP gene, which encodes arachidonate 5-lipoxygenase-activating protein, reportedly conferred an increased risk of myocardial infarction and stroke, independent of conventional risk factors." (PMID 25210744, 2014). "Therefore, we infer that AY212271 may participate in the inflammatory response in the border zone of myocardial infarction indirectly through Alox5ap." (PMID 31827539, 2019). "In the last two decades, several genetic variants of the ALOX5AP gene, which encodes FLAP, have been investigated for their potential contribution to cardiovascular and cerebrovascular diseases, including coronary artery disease (CAD), myocardial infarction (MI), and ischemic stroke (IS)." (PMID 41390442, 2025). "Analysis of angiographic data showed a possible modest role for ALOX5AP in the development of atheroma, but not on its clinically manifest forms, such as myocardial infarction." (PMID 36011386, 2022). "Polymorphisms in two 5-LO pathway genes; 5-lipoxygenase activating protein (ALOX5AP) and leukotriene A4 hydrolase (LTA4H) have shown an association with LTB4 overproduction from ionomycin-stimulated neutrophils and with myocardial infarction (MI) susceptibility." (PMID 23167751, 2012). "Single nucleotide polymorphisms (SNPs) in two 5-LO pathway genes; 5-lipoxygenase activating protein (ALOX5AP) and leukotriene A4 hydrolase (LTA4H) have shown an association with LTB4 overproduction from ionomycin-stimulated neutrophils and with myocardial infarction (MI) susceptibility." (PMID 22206291, 2011).
Stroke (19 papers, 2008 to 2025). Sudden impairment of blood flow to a part of the brain due to occlusion or rupture of an artery to the brain. "Variations in ALOX5AP gene are associated with CVDs, stroke and others because of their possible effects on ALOX5AP stability and function." (PMID 40737279, 2025). "ALOX5AP expression is increased in patients of obesity and insulin resistance and recognized as a susceptibility gene for stroke, but its role in cancer genesis and progression has not been investigated." (PMID 33987033, 2021). "As a matter of fact, evaluating ALOX5AP polymorphism in different populations seems necessary to establish regional guidelines about genetic risk factors for developing stroke." (PMID 31749932, 2019). "During 1-year period of this study, ALOX5AP gene polymorphism in 200 healthy patients (control group) as well as 228 patients with stroke (case group) was evaluated by polymerase chain reaction-restriction fragment length polymorphism (PCR-RFLP)." (PMID 31749932, 2019). "Different studies have provided different relations between ALOX5AP promoter polymorphism (rs17222919) and stroke." (PMID 31749932, 2019). "In humans, a genetic variant of the gene ALOX5AP, encoding 5-lipoxygenase activating protein (FLAP), is associated with two times greater risk of stroke by increasing leukotriene production and inflammation." (PMID 28607533, 2017). "Human genetic studies have demonstrated a significant correlation between stroke risk and polymorphisms in several of the LT-associated genes, e.g. ALOX5AP encoding FLAP, as well as genes encoding LTC4 synthase and cysteinyl (Cys) LT receptors." (PMID 23194405, 2012). "Two at-risk haplotypes (HapA and HapB) for stroke had been identified in the ALOX5AP gene." (PMID 22849376, 2012). "Since a genome-wide linkage analysis conducted by the deCODE group in an Icelandic population suggested that a four-SNP haplotype in the ALOX5AP gene conferred a nearly two times greater risk of stroke, several groups attempted to replicate the association of ischemic stroke with ALOX5AP variants." (PMID 23554707, 2011). "Functional polymorphisms of LT-related genes (such as ALOX5AP) may thereby enhance the susceptibility to stroke." (PMID 23554707, 2011). "A previous study highlighted the implication of single nucleotide polymorphisms (SNPs) and at-risk haplotypes in the arachidonate 5-lipoxygenase-activating protein (ALOX5AP) gene, conferring an increased risk of suffering from stroke in the Icelandic population through genome-wide linkage scan." (PMID 23554707, 2011). "Different sample sizes, SNP detection methods, statistical tests, and inclusion criteria are 4 major variations in similar studies about the relation of ALOX5AP and stroke." (PMID 31749932, 2019). "In addition the ALOX5AP gene variations are associated with CAD risk in patients with familial hypercholesterolemia, stroke in Iranian, Chinese, and premature CAD in European American patients." (PMID 40737279, 2025). "The authors concluded that to date, the cumulated evidence did not support an association of ALOX5AP variants and risk of stroke, though they cautioned that the conclusion was based on a relatively small number of studies." (PMID 22849376, 2012). "Moreover, TOAST subtype analysis of ischemic stroke cases showed non-significant association with genetic variants in ALOX5AP, although varied risk factors and phenotypic differences among ischemic stroke are mainly related to different stroke etiologies." (PMID 23554707, 2011). "At gene level, few were differentially expressed: ALDH2, ALOX5AP, F13A1, and IMPA2 (males, all stroke); ITGB3 (females, cardioembolic); ADD1 (males, atherosclerotic); F13A1, IMPA2 (males, lacunar); and WNK1 (females, lacunar)." (PMID 33193047, 2020). "Two widely investigated genes, phosphodiesterase 4 D (PDE4D) and lipoxygenase-activating protein (ALOX5AP), have never been confirmed in meta-analyses of stroke." (PMID 23356535, 2013).
atherosclerosis (15 papers, 2010 to 2025). A disease characterized by the build-up of fatty material and calcium deposition in the arterial wall resulting in partial or complete occlusion of the arterial lumen. "In animal models, ALOX5AP deficiency reduces the size and complexity of atherosclerotic plaques, suggesting a critical role in the development of atherosclerosis." (PMID 37189834, 2023). "Polymorphisms within ALOX12, ALOX5, and ALOX5AP are genetically associated with subclinical atherosclerosis and with biomarkers of disease in families with type 2 diabetes." (PMID 20592751, 2010). "The ALOX12, ALOX15, ALOX5, and ALOX5AP genes represent strong candidates for atherosclerosis risk, especially in the context of type 2 diabetes." (PMID 20592751, 2010). "Therefore, various polymorphisms of the ALOX5AP gene are associated with atherosclerosis, coronary artery disease, and ischemic stroke." (PMID 36673783, 2023). "We hypothesize that polymorphisms in ALOX12, ALOX15, ALOX5, and ALOX5AP genes are associated with subclinical atherosclerosis in multiple vascular beds." (PMID 20592751, 2010). "The ALOX5AP is important for the synthesis of leukotrienes, which is involved in inflammatory reactions and dysregulation of leukotrienes production results in atherosclerosis." (PMID 40737279, 2025). "5-lipoxygenase (ALOX5AP) is abundantly expressed in the arterial wall of patients with different lesion stages of atherosclerosis." (PMID 40868093, 2025). "Arachidonate 5-lipoxygenase-activating protein (ALOX5AP) plays an important role in atherosclerosis pathogenesis." (PMID 36673783, 2023). "The identified atherosclerosis-associated candidate genes include lipoprotein receptor-related protein 6 (LRP6) at 12q13.2, arachidonate 5-lipoxygenase-activating protein (ALOX5AP) at 13q12-13, and myocyte enhancer factor 2A (MEF2A) at 15q26.3." (PMID 32197550, 2020). "Variants of the arachidonate 5-lipoxygenase-activating protein (ALOX5AP) gene have been suggested to play an important role in the pathogenesis of atherosclerosis and ischemic stroke." (PMID 23554707, 2011). "Other mouse studies have reported the involvement of LT pathway genes in atherosclerosis related traits as well, including the LT receptors and ALOX5 activating protein (ALOX5AP)." (PMID 30678701, 2019).
ischemic stroke (15 papers, 2011 to 2025). A stroke disorder caused by obstruction of blood flow to the brain, due to thrombotic (local blood clot formation) or embolic (due to a blood clot or other material traveling from another site) event. "It should be noted that analysis of ALOX5AP polymorphisms showed different evidence for associations with the risk of ischemic stroke." (PMID 36011386, 2022). "The present study has been conducted in order to evaluate the relation between genetic polymorphism of ALOX5AP gene and developing ischemic stroke in north east of Iran." (PMID 31749932, 2019). "According to our results, ALOX5AP promoter polymorphism (rs17222919) is significantly related to increased risk of ischemic stroke." (PMID 31749932, 2019). "According to our results, ALOX5AP polymorphism is associated with increased risk of ischemic stroke in our population." (PMID 31749932, 2019). "A two-stage study design was used to explore the relationship between variants in the transcriptional regulatory region of ALOX5AP gene and ischemic stroke (IS) risk in Chinese populations." (PMID 27416969, 2016). "The purpose of this study was to study the possible association of 7 variants of ALOX5AP, rs4073259, rs4769874, rs9315050, rs9551963, rs10507391, rs9579646, and rs4147064 with ischemic stroke in the population with Han ancestry in northern China." (PMID 22849376, 2012). "This study was aimed to explore the association of ALOX5AP variants with ischemic stroke risk in Han Chinese of eastern China." (PMID 23554707, 2011). "The present study examined the association between variants of ALOX5AP and the risk of ischemic stroke in a Chinese Han population of eastern China." (PMID 23554707, 2011). "In addition, rs4073259, rs9579646, rs9551963, rs9315050, rs9551963 and the rs4073259 SNPs of ALOX5AP were linked with ischemic stroke in Chinese Han population." (PMID 40737279, 2025). "Genetic variations in the oxidative stress-related genes ALOX5, ALOX5AP, and MPO have also been shown to modulate susceptibility to ischemic stroke through the main effects and epistatic interactions." (PMID 36011386, 2022). "Although PAD has a clinical and pathophysiological correlation with CAD and ischemic stroke, no study has examined the link between genetic polymorphisms of the ALOX5AP gene and PAD." (PMID 36673783, 2023). "For example, polymorphisms in the Arachidonate 5-lipoxygenase activating protein (ALOX5AP) gene were associated with ischemic stroke in White Americans but not in African Americans." (PMID 34828431, 2021).
asthma (10 papers, 2011 to 2023). "ALOX5AP plays a role in the 5-lipoxygenase (LO) pathway, which is known causative factors of asthma, allergy and atopy." (PMID 26382838, 2015). "Genome-wide gene and methylation expression profiles of nasal polyps in aspirin-intolerant asthma patients showed upregulation of ALOX5AP gene expression in nasal polyps whereas its methylation level was decreased." (PMID 36059464, 2022). "Polymorphisms spanning genes involved in the production of leukotriene B4 (LTB4) e.g. ALOX5AP and LTA4H are associated with asthma susceptibility, suggesting a role for LTB4 in disease." (PMID 23167751, 2012). "We and others have recently provided preliminary evidence that SNPs spanning ALOX5AP and LTA4H are asthma susceptibility markers and determinants of lung function." (PMID 23167751, 2012). "We retrospectively evaluated SNPs spanning ALOX5AP (8 SNPs) and LTA4H (6 SNPs) that encode for proteins involved in LTB4 production and had previously been associated with asthma susceptibility with BTS defined severity (step 1–5)." (PMID 23167751, 2012). "We have recently reported evidence that SNPs spanning ALOX5AP and LTA4H are asthma susceptibility markers." (PMID 22206291, 2011). "We have previously shown evidence that polymorphisms within genes controlling leukotriene B4 (LTB4) production (ALOX5AP and LTA4H) are associated with asthma susceptibility in children." (PMID 22206291, 2011). "Previous studies on the genome-wide gene expression profile of CRSwNP showed increased ALOX5AP gene expression levels in the nasal polyps of patients with aspirin-intolerant asthma and decreased methylation levels of ALOX5AP in a genome-wide methylation profile of nasal polyps." (PMID 33603773, 2021). "Interestingly, there was modest evidence for a role of ALOX5AP and LTA4H SNPs associated with BTS defined asthma severity." (PMID 23167751, 2012).